TK1 (thymidine kinase 1)
Diseases named in the same sentence as TK1 in open-access papers (continued):
Sharing a sentence is not in itself a finding about the gene and the disease.
prostate carcinoma (continued). "Since 1960, scientists have discovered heightened amounts of TK1 in the blood of individuals afflicted with various forms of cancer, such as lung, colon, breast, and prostate cancer." (PMID 39803822, 2025). "In examining WHO grade groups, the clear trend of increasing TK1 levels with advancing tumour grade substantiates the enzyme’s capability to mirror the biological severity of prostate cancer." (PMID 40830177, 2025). "TK1 and FORα were significantly increased in prostate cancer patients compared to the control group (mean 28.11pg/ml vs. 15.66 pg/ml, p-value < 0.001) and (median 1686.4 pg/ml vs. 437.2 pg/ml, p-value < 0.001) respectively." (PMID 40830177, 2025). "The study aimed to assess the potential role of Thymidine Kinase one (TK1) and folate receptor alpha (FORα) in prostate cancer." (PMID 40830177, 2025). "An assay utilizing an antibody to capture prostasomes and then detection of TK1 activity would be a potentially valuable assay for, e.g., monitoring of prostate cancer, but further studies will be needed." (PMID 39006942, 2024). "•TK1 enzyme activity is higher in small extracellular vesicles (sEV) derived from prostate cancer cell lines compared to the normal prostate epithelial cell line and prostasome." (PMID 39006942, 2024). "Here, we investigate the TK1 enzyme activity in prostasomes from healthy individuals and sEVs from three malignant cell lines derived from prostate cancer." (PMID 39006942, 2024). "TK1 is critical in DNA recycling before cell division and is regarded as a potential marker for prostate cancer prognosis." (PMID 39006942, 2024). "This study aimed to investigate TK1 enzyme activity in prostasomes isolated from seminal fluids and in sEVs of up to 200 nm derived from prostate cancer cell lines." (PMID 39006942, 2024). "The results suggested that high expression of SNHG4 was correlated with RRM2/EZH2/AURKA/TK1 overexpression in prostate cancer tissue specimens." (PMID 37596700, 2023). "The TK1 protein levels in prostate cancer sera ranged from 0.14 to 1.64 ng/mL (mean ± SD = 0.44±0.33 and median = 0.30) and were significantly higher compared to blood donors." (PMID 36201558, 2022). "The results indicated that TK1 ablation in prostate cancer cells leads to cell arrest in G2/M phase compared to control cells." (PMID 35559045, 2022). "In lung adenocarcinoma and BC cell lines, TK1 has been found to support tumor growth; bioinformatic evidence points to a similar role for TK1 in adrenocortical carcinoma and prostate cancer patients." (PMID 36358602, 2022). "Combined, this suggests the importance TK1 plays in prostate cancer progression, especially in cells under metabolic restriction." (PMID 29262598, 2017). "Size-exclusion analysis of sera from breast and prostate cancer showed that the detected active TK1 was primarily a high molecular weight complex, similar to the forms found in sera from MDS patients and blood donors." (PMID 25881026, 2015). "In sera from prostate cancer patients, the majority of TK1 protein eluted with a peak at approximately 100 kDa, and only a minor fraction eluted in the high-MW form." (PMID 25881026, 2015). "Whereas in breast and prostate cancer sera, the TK1 elution profile was different and the TK1 activity eluted as a major peak with high MW, while the TK1 protein eluted in multimeric forms with different MW, representing both active and inactive forms of TK1." (PMID 25881026, 2015). "In serum from a prostate cancer patient, very low TK1 activity levels were noted in fractions corresponding to the MW range 200-720 kDa." (PMID 25881026, 2015). "This indicates that TK1 might be a useful biomarker for the aggressiveness of prostate cancer, as higher Gleason scores generally represent more advanced and aggressive forms of the disease." (PMID 40830177, 2025). "TK1 & FORα could serve as biomarkers for prostate cancer diagnosis and prognosis offering a novel treatment approach." (PMID 40830177, 2025).
prostate carcinoma (continued). "Furthermore, recently, it was found that TK1 is identified as an independent variable of overall survival (OS) of prostate cancer, showing statistical significance when combined with total PSA levels." (PMID 40830177, 2025). "Hence, the authors concluded that high levels of TK1 predict death in prostate cancer within 30 years of follow-up6." (PMID 40830177, 2025). "However, the TK 210 ELISA (sensitivity = 44%) showed significantly higher sensitivity compared to the TK1 activity assay (sensitivity = 25%) in differentiation of prostate cancer sera compared to of blood donors at a specificity of 98%." (PMID 36201558, 2022). "Methods based on anti-TK1 antibodies and 3H-dThd phosphorylation for determining the specific activity of serum TK1 strongly indicate that there is a large fraction of inactive TK1, particularly in sera from patients with breast and prostate cancer." (PMID 25881026, 2015). "The measurement of TK1 activity in EVs may be essential in future prostate cancer studies." (PMID 39006942, 2024). "However, the relationship between methylation status of TK1 and Immune Infiltrates in Prostate Cancer (PCa) is unknown." (PMID 36035114, 2022). "For predicting the presence of metastasis among prostate cancer patients, higher PSA and TK1 levels were considered independent predictors for metastasis." (PMID 40830177, 2025). "We assumed that SNHG4 facilitates prostate cancer cell proliferation, the cell cycle and senescence by regulating RRM2, EZH2, AURKA and TK1." (PMID 37596700, 2023). "We combined serum TK1 with PSA and evaluated its capacity to predict overall survival (OS) in 175 men with prostate cancer (PCa), detected by screening in 1988–1989 (n = 52) and during follow-up (median 22.6 years) (n = 123)." (PMID 36982234, 2023). "TK1 has also been identified bioinformatically among differentially expressed genes (DEGs) as a hub gene involved in adrenocortical carcinoma (ACC) and prostate cancer (PCa) pathogenesis." (PMID 33292474, 2020). "CKS2, TK1, MKI67, TOP2A, CCNB1 and RRM2 directly related to the recurrence and prognosis of prostate cancer." (PMID 32266115, 2020). "To determine our prediction, we found CCNB1, CKS2, MKI67, RRM2, TK1 and TOP2A acted as independent prognostic factors in TCGA prostate cancer." (PMID 32266115, 2020). "In this study, we measured both serum TK1 activity and TK1-25-kDa protein levels in MDS, breast and prostate cancer patients." (PMID 25881026, 2015). "Serum TK1 protein (25 kDa polypeptide) levels were also significantly higher in MDS, breast, prostate cancer compared to blood donors (mean ± SD = 19 ± 9, 22 ± 11, 20 ± 12, and 5 ± 3.5 ng/mL, respectively)." (PMID 25881026, 2015). "The mean specific activity of TK1 in sera from blood donors and MDS patients was significantly higher (approx. 2-fold) compared with activities in sera from breast and prostate cancer patients." (PMID 25881026, 2015). "However, Western blotting demonstrated high TK1 25 kDa protein levels in fractions lacking TK1 activity in sera from cases with breast and prostate cancer." (PMID 25881026, 2015). "The varying compositions of the TK1 oligomers in sera from different patients may also explain the differences in specific activities of TK1 observed in sera from blood donors and MDS patients compared with those in sera from breast or prostate cancer patients." (PMID 25881026, 2015).
lymphoma (17 papers, 2011 to 2025). A malignant (clonal) proliferation of B- lymphocytes or T- lymphocytes which involves the lymph nodes, bone marrow and/or extranodal sites. "Studies in horses are limited, but preliminary studies report promising diagnostic value, especially for thymidine kinase 1, which was already studied as a proliferation marker in case of lymphoma in horses." (PMID 41150147, 2025). "Elevated levels of TK1 in the blood has been associated with various types of cancers, including lymphoma, leukemia, and solid tumors and higher levels of TK1 correlates with advanced stage of disease as well as poor prognosis." (PMID 40351765, 2025). "C-reactive protein, thymidine kinase 1, and haptoglobin have been most extensively studied and commercialized in diagnostic tests, the TK Canine Cancer Panel and the Canine Lymphoma Blood Test." (PMID 27747218, 2016). "Furthermore, fluctuations in TK1 protein levels during the course of chemotherapy in dogs with lymphoma closely associated with clinical outcome." (PMID 26366881, 2015). "In contrast to the canine TK1 ELISA, both the lymphoma and solid tumors groups exhibited slightly lower AUC values of 0.71." (PMID 40351765, 2025). "This is the first report of the development and application of a sandwich monoclonal TK1 ELISA with sera from healthy dogs and dogs with lymphoma." (PMID 37808109, 2023). "The IP results with Mab-2 showed that 90% of the recombinant canine TK1 was able to bind to the beads at 4°C and 23°C, while 40–60% of TK1 were bound to the beads when serum samples from dogs with leukemia, lymphoma and histiocytic sarcoma were analyzed." (PMID 37808109, 2023). "Serum TK1 protein levels were significantly higher in dogs with lymphoma compared to those in healthy dogs (p < 0.0001)." (PMID 37808109, 2023). "The aim of this study was to develop a canine specific Thymidine kinase 1-ELISA, to contribute to the diagnosis of malignant lymphomas in dogs." (PMID 37808109, 2023). "Dogs with lymphoma: The TK1 concentrations in the lymphoma group were in the range from 0.10 to 10.6 ng/mL (median 0.47 ng/mL), thus significantly higher compared to healthy dogs." (PMID 37808109, 2023). "In case of healthy dogs, a weak correlation was found between canine TK1 ELISA and dThd phosphorylation assay (rs = 0.34), while the correlation was significantly higher between the assays in the lymphoma group (rs = 0.9)." (PMID 37808109, 2023). "In most of these studies, it has been shown that the activity of TK1, measured by radioenzymatic assays or ELISA, is increased particularly in the blood of dogs suffering from lymphomas and myeloid leukaemia compared with healthy dogs." (PMID 35815441, 2022). "The use of commercially available TK1 activity assays has previously demonstrated that S-TK1 activity measurements can give information concerning prognosis and treatment monitoring mainly for patients with leukemia and lymphomas." (PMID 36201558, 2022). "Serum TK1 activity in horses can be transiently elevated with inflammatory conditions and is consistently elevated in horses with lymphoma." (PMID 34359096, 2021). "Serum TK1 activity levels were significantly higher in horses with lymphoma (p < 0.0005) and suspected lymphoma (p < 0.02) and in tumour-free groups with diverse diseases (p < 0.03) than in controls without concurrent diseases." (PMID 34906077, 2021). "Serum TK1 activity in samples from felines with malignant lymphoma ranged from 1.5 to 13.3 pmol/min/ml, all of which were clearly above the cutoff value." (PMID 34579716, 2021). "In contrast, dogs with leukemia and lymphoma showed marked increases in TK1 activity, when compared to dogs with inflammatory disease, healthy controls, and those in remission." (PMID 34359096, 2021). "Thymidine kinase 1 (TK1) is another interesting serum biomarker that has been used for prognosis and monitoring therapy in leukemia and lymphoma patients during the last two decades." (PMID 27079872, 2016).
lymphoma (continued). "Serum TK1 activity in dogs with lymphoma was significantly higher than that of normal dogs or dogs with inflammation or other tumors." (PMID 27747218, 2016). "Serum TK1 activity has been used for prognosis and monitoring of leukemia and lymphoma patients for many years." (PMID 27079872, 2016). "Because of this characteristic, TK1 has been used as a proliferation marker in lymphomas and leukemias in human medicine for many years." (PMID 27079872, 2016). "Further, serum TK1 activity was significantly higher in high-stage (≥stage 3 disease) than in low-stage lymphoma patients." (PMID 27747218, 2016). "First reported in dogs in 2004, serum TK1 has been evaluated as a tool for both prognosis and disease monitoring of lymphoma." (PMID 27747218, 2016). "Utilizing a radio-enzyme assay, serum samples from 21 healthy beagles, 8 juvenile beagles, and 65 dogs with lymphoma were evaluated for TK1 activity." (PMID 27747218, 2016). "The reason for this is most likely related to differences in specific activity of serum TK1 since previous size exclusion analysis showed that serum TK1 exist as enzymatically active high molecular weight aggregates in dogs with lymphoma." (PMID 26366881, 2015). "Here we also showed that TK1 protein levels returned to normal levels during chemotherapy of dogs with lymphoma, indicating disease remission." (PMID 26366881, 2015). "Serum TK1 activity measurement is an established tool for diagnosis and monitoring of lymphomas and leukemias in human medicine." (PMID 26366881, 2015). "In two dogs with progressive lymphoma, the TK1 protein levels increased and these relapsed patients were euthanized." (PMID 26366881, 2015). "Others also found high levels of PCNA positivity in DLBCLs and similar levels of TK-1 activity in low- and high-grade lymphoma." (PMID 24397937, 2014). "A form of TK1 is found at high levels in the sera of humans and animals with malignant tumors; therefore, serum TK1 activity has been used as a prognostic marker for several different tumor types, but primarily in leukemia and lymphoma." (PMID 22741536, 2012). "Recently serum TK1 activity has been used as biomarker for the diagnosis and prognosis of canine malignant lymphoma and leukemia." (PMID 22741536, 2012). "However, the ROC curve analysis demonstrates that Canine TK1 ELISA had higher sensitivity compared to the two activity assays in differentiating lymphoma from the healthy dog subgroups." (PMID 37808109, 2023). "A few reports of utilising TK1 as a biomarker of hematopoietic tumours in horses (lymphoma and multiple myeloma) were quite promising, but other studies showed that its performance is below expectations because false‐negative and false‐positive results are reported." (PMID 36495211, 2023). "The TK1 activity levels in the healthy group were in the range of 0.50 to 62 pmol/min/mL (median was 2.8 pmol/min/mL), and there was a significant difference between the healthy and lymphoma groups." (PMID 37808109, 2023). "A link between equine herpesvirus‐5 and lymphoma was described in a few case reports, and a potential cross‐reactivity between cellular (equine TK1) and viral (herpes) thymidine kinase should be further examined." (PMID 36495211, 2023). "Finally, several studies have investigated the interest of TK1 as a pharmacodynamic biomarker in dogs with haematopoietic tumours (lymphomas and leukaemias) during treatment." (PMID 35815441, 2022). "Serum TK1 activity was significantly higher in horses with lymphoma than in controls." (PMID 34906077, 2021). "Thymidine kinase 1 (TK1) assay is a potentially useful biomarker for lymphoma in horses." (PMID 34359096, 2021). "Furthermore, in felines with lymphoma serum TK1 activity returned to normal levels in response to treatment." (PMID 34579716, 2021).
lymphoma (continued). "Indeed, in this study, we were able to show that the serum TK1 activity in horses with confirmed lymphoma was significantly higher than the activities in control horses with and without concurrent diseases." (PMID 34906077, 2021). "ROC (receiver operating characteristic) analysis was conducted to evaluate the utility of serum TK1 as a biomarker and revealed a sensitivity of 0.86, a specificity of 0.95 and an AUC (area under the curve) of 0.92 for the confirmed lymphoma group using a cut-off of ≤0.65 pmol/min/ml." (PMID 34906077, 2021). "In the tumour-free control group with concurrent diseases, there were 5 out of 107 horses with serum TK1 activity above the cut-off value, and in the confirmed and suspected lymphoma groups, there was 1 horse in each group with serum TK1 activity below the cut-off value." (PMID 34906077, 2021). "Our ROC analysis revealed an AUC value of 0.98, a sensitivity value of 0.83 and specificity value of 0.95 for lymphoma group, suggesting that serum TK1 may be a promising biomarker for lymphoma diagnostics and treatment monitoring." (PMID 34579716, 2021). "Additionally, we included a small cohort of horses with clinical signs highly suggestive of lymphoma, for which measurement of TK1 activity further corroborated this presumptive diagnosis." (PMID 34906077, 2021). "Since equine lymphoma is a disease with many faces and usually unspecific symptoms, a reliable blood-based biomarker such as TK1 would greatly assist in the noninvasive identification of horses with lymphoma in not only advanced but also early stages of cancer." (PMID 34906077, 2021). "Serum TK1 activity is used as a marker of lymphoma in dogs and cats." (PMID 34359096, 2021). "It was clear that these antibodies detected cellular TK1 in canine lymphoma tissues." (PMID 26366881, 2015). "Furthermore, serum samples from 7 dogs with lymphoma were followed during therapy with the TK1 activity and protein assays." (PMID 26366881, 2015). "Moreover, TK1-ELISA had significantly higher ability to distinguish lymphoma cases from healthy based on receiver operating characteristic analyses (area under the curve, AUC, of 0.96) to that of the activity assay (AUC, 0.84)." (PMID 26366881, 2015). "A serum sample from dogs with lymphoma with low TK1 activity (3 pmole/min/ml) was also analyzed." (PMID 22741536, 2012). "Furthermore, canine TK1-ELISA were developed by using the combination of peptide-based monopoly and poly-polyclonal dog TK1 antibodies for diagnosis and therapy monitoring of dog lymphomas." (PMID 40351765, 2025). "Serum TK1 activity can be measured using a radioactive substrate analogue (Prolifigen TK-REA) and this radio-enzymatic assay has been used in dogs with malignant lymphoma to predict the relapse of disease and to follow up therapy." (PMID 22741536, 2012). "For instance, TK1 levels do not consistently correlate with survival or advanced disease stages despite the increase in multicentric lymphoma." (PMID 39682357, 2024). "We also observed that serum TK1 activity in felines with IBD or inflammatory disease was within the range of normal healthy ones, and serum TK1 activity returned to normal levels in response to treatment in felines with lymphoma." (PMID 34579716, 2021). "Serum samples collected from felines with confirmed IBD or inflammatory disease (n = 2) but not lymphoma had serum TK1 activity ≤0.5 pmol/min/ml, which is within the normal range." (PMID 34579716, 2021). "Serum TK1 activity was measured in samples collected from horses with confirmed or suspected lymphoma and control horses with and without concurrent diseases." (PMID 34906077, 2021). "Although the sensitivity and specificity for the solid tumor group were not as good as the lymphoma group, the overall serum TK1 activity in this group was significantly higher than that of the healthy group." (PMID 34579716, 2021).